DYNC1H1 (dynein cytoplasmic 1 heavy chain 1)
Diseases named in the same sentence as DYNC1H1 in open-access papers (continued):
Sharing a sentence is not in itself a finding about the gene and the disease.
tumor (11 papers, 2020 to 2025). "Together, these results indicated that mutant DYNC1H1 was strongly associated with enhanced tumor immune activity." (PMID 33221769, 2020). "To further explore how mutant DYNC1H1 increase drug sensitivities of MTIs, we used a differential analysis method to identify mutant DYNC1H1 related genes by comparing DYNC1H1 mutated tumor with wild type tumors (37/338) in TCGA-STAD." (PMID 33221769, 2020). "Overall, KLF1 silencing downregulated the LINC02159/DYNC1H1 pathway to inhibit tumor growth in vivo." (PMID 40798857, 2025). "According to the DYNC1H1 expression, the 424 tumor samples were classified into two groups, with 212 samples in the high expression of the DYNC1H1 group and 212 samples in the low-expression group." (PMID 35601740, 2022). "Using the Tumor Immunoassay Resource (TIMER) and CIBERSORT algorithm, we further investigated the interrelationship between DYNC1H1 and Tumor-Infiltrating Immune Cells (TIICs)." (PMID 35601740, 2022). "Through DYNC1H1 analysis, and its interrelation to multiple tumor characteristics and immune cell responses, high DYNC1H1 expression served as an independent prognostic factor for poor OS." (PMID 35601740, 2022). "Altogether, these results showed that DYNC1H1 was expected to be the positive predictive tumor marker for patients with LIHC." (PMID 35601740, 2022). "KLF1 silencing inhibited tumor growth in vivo by downregulating the LINC02159\DYNC1H1 pathway." (PMID 40798857, 2025). "Furthermore, DYNC1H1 leads to enhanced tumor metastasis and poor prognostic outcomes in patients with NSCLC." (PMID 40798857, 2025). "Furthermore, we sought to figure out whether the tumor immune microenvironment was distinct in LIHC patients with low DYNC1H1 compared to those with high DYNC1H1." (PMID 35601740, 2022). "Quantitative real-time PCR (qRT-PCR) exhibited that expression of CPS1 and PTPRB was downregulated in tumor tissues compared with paracancerous tissues, while MAP2, DYNC1H1, and MKI67 were overexpressed in tumor tissues." (PMID 35311113, 2022). "The expression of MAP2, DYNC1H1, and MKI67 was obviously higher expressed in tumor tissues, while CPS1 and PTPRB were downregulated in tumor tissues compared with normal tissues in TCGA dataset." (PMID 35311113, 2022). "The immunohistochemistry (IHC) results demonstrated that DYNC1H1, GTPBP4, PRKDC, RBM19, SF3B4, SPATS2 and TAF9 were significantly increased in HCC tumor cells compared to normal hepatocytes." (PMID 33411682, 2020).
cancer (10 papers, 2020 to 2025). A tumor composed of atypical neoplastic, often pleomorphic cells that invade other tissues. "Accordingly, the mutation frequency of DYNC1H1 was positively associated with TMB levels in 9 cancers." (PMID 33221769, 2020). "Furthermore, we investigated the importance of mutant DYNC1H1 in TCGA pan-cancer, showing that the mutation frequency of DYNC1H1 was 0.4%-19.7%, average mutation frequency was 5.17% in 15 cancers." (PMID 33221769, 2020). "Furthermore, some MTIs activities were positively associated with mutant Dynein Cytoplasmic 1 Heavy Chain 1 (DYNC1H1) (p < 0.05) based on NCI-60 cancer cell line panel." (PMID 33221769, 2020). "DYNC1H1 serves as an intriguing biomarker in different kinds of cancers, as the variance in its mRNA stability could alter cancer cell repair, metabolism, and invasion." (PMID 40798857, 2025). "Finally, the enhanced crosslinking and immunoprecipitation (eCLIP) analyses reveal that FXR1 binds with the G4-enriched mRNA targets such as AHNAK, MAP1B, AHNAK2, HUWE1, DYNC1H1 and UBR4 and controls its mRNA expression in cancer cells." (PMID 38709899, 2024). "Mutant DYNC1H1 significantly positively correlated with TMB-H and MSI-H in GC or various cancers." (PMID 33221769, 2020). "The results showed that ADA, ATP1B3, DYNC1H1 and FTCD were differently expressed in non-cancer vs. cancer tissues of different stages, in cancer tissues of stage I vs. stage II or stage I vs. stage III." (PMID 35739471, 2022).
neurodevelopmental disorder (9 papers, 2022 to 2026). A behavioral and cognitive disorder with onset during the developmental period that involves impaired or aberrant development of intellectual, motor, or social functions. "Variants in DYNC1H1 have been implicated in several neurodevelopmental disorders including ID and ASD." (PMID 35363276, 2022). "DYNC1H1-NMD refers to DYNC1H1-related neuromuscular disorders while DYNC1H1-NDD refers to DYNC1H1-related neurodevelopmental disorders." (PMID 39457418, 2024).
neurological diseases (8 papers, 2020 to 2025). "Mutations in DYNC1H1 gene have been associated with neurological diseases in humans and here we show Pcyt2 + /- mice exhibit decreased methylation and expression." (PMID 40153413, 2025). "A number of rare neurological diseases have been genetically associated with mutations in the DYNC1H1 gene." (PMID 36218033, 2023). "Various mutations in human DYNC1H1 have been associated with neurological diseases, including spinal muscular atrophy, Charcot–Marie–Tooth disease, and infantile developmental and epileptic encephalopathy." (PMID 36218033, 2023). "Mutations in this DYNC1H1 gene may potentially contribute to neurological disorders, resulting in neuromuscular and sensory deficits." (PMID 37807632, 2023). "Mutant DYNC1H1 was reported to impede the ATP hydrolysis cycle which help bind to MTs in the neurological diseases." (PMID 33221769, 2020). "The nervous system disease class consists of proteins APP, DYNC1H1, DYNC1I2, HINT1, LSM2, RNF11, SNCA in between 30% and 40% association." (PMID 34918006, 2022).
neurodegenerative disease (4 papers, 2010 to 2022). A disorder of the central nervous system characterized by gradual and progressive loss of neural tissue and neurologic function. "This CpG belongs to the gene DYNC1H1, which is associated with neurological and neurodegenerative diseases." (PMID 36259657, 2022). "To date, most researches regarding DYNC1H1 mutation have focused on neurodegenerative diseases." (PMID 34272765, 2021). "Variations in DYNC1H1 gene have been repeatedly reported to be involved in the pathogenesis of neurodegenerative diseases." (PMID 34272765, 2021).
neuromuscular disease (4 papers, 2022 to 2025). "Although numerous cases have been reported worldwide, the analysis of the genotype–phenotype correlations between DYNC1H1 mutations and neuromuscular diseases, including SMALED1 and CMT2O, is still scarce." (PMID 35899263, 2022). "Genotype–phenotype analysis of DYNC1H1 variants and neuromuscular diseases revealed that mutations in the DYN1 region of DYNC1H1 protein were associated with a more severe phenotype, more complicated symptoms, and more CNS involvement than the DHC_N1 region." (PMID 35899263, 2022). "Next, we analyzed the correlation between clinical phenotypes of neuromuscular diseases and different mutation sites of DYNC1H1 protein." (PMID 35899263, 2022). "Spinal muscular atrophy with lower extremity predominance 1 (SMALED1) and Charcot–Marie-Tooth diseasetype 2O (CMT2O) are two kinds of hereditary neuromuscular diseases caused by DYNC1H1 mutations." (PMID 35899263, 2022). "We provided a detailed description of the clinical and genetic spectrum of neuromuscular diseases caused by DYNC1H1 mutations by reviewing previous publications." (PMID 35899263, 2022). "Next, we reviewed previous publications and summarized the phenotypic and genetic characteristics of neuromuscular diseases caused by DYNC1H1 mutations." (PMID 35899263, 2022). "Our study potentially expanded the knowledge of the phenotypic and genetic spectrum of neuromuscular diseases caused by DYNC1H1 mutations." (PMID 35899263, 2022). "To further explore the phenotypic and genetic spectrum of DYNC1H1 mutations, we then analyzed the genotype–phenotype correlations between DYNC1H1 variants and neuromuscular diseases." (PMID 35899263, 2022). "Despite the limitations, our study provided a comprehensive summary of the DYNC1H1 mutation spectrum by selecting relevant neuromuscular diseases, especially SMALED1 and CMT2O, and unraveled the hidden correlation between genotypes and phenotypes." (PMID 35899263, 2022). "First, we analyzed whether there was any correlation between the types of DYNC1H1 mutations and the kinds of neuromuscular diseases." (PMID 35899263, 2022). "A total of 105 patients with neuromuscular diseases were reported carrying DYNC1H1 mutations." (PMID 35899263, 2022). "These articles identified 39 distinct variants in DYNC1H1 related to neuromuscular diseases." (PMID 35899263, 2022). "Previous publications were searched to further explore the clinical and genetic spectrums of DYNC1H1-related neuromuscular diseases." (PMID 35899263, 2022). "Of all the DYNC1H1 mutations leading to neuromuscular diseases in the current study, none were located in Dynein_C." (PMID 35899263, 2022).
infection (3 papers, 2014 to 2021). The state of being infected such as from the introduction of a foreign agent such as serum, vaccine, antigenic substance or organism. "While downregulation of MYO6, involved in actin-based motility, did not influence MHV infection (dark orange), our results indicate that the microtubule-associated motility proteins DYNC1H1 and DYNC2H1 are important for infection with MHV (orange)." (PMID 25375324, 2014).
brain disease (2 papers, 2015 to 2021). "The network revealed that the majority of the disorders are linked with DYNC1H1 (k = 91), LMNA (k = 86), FMR1 (k = 74), DCTN1 (k = 57), and ALDH18A1 (k = 54) genes and showed interactions with multiple brain disorders." (PMID 34832615, 2021).
peripheral neuropathies (2 papers, 2021 to 2024). "Thus, it is expected that the pathogenic human DYNC1H1 variant causing peripheral neuropathy will also impair mitochondrial transport and morphology, though this remains to be confirmed." (PMID 33810506, 2021).
DYNC1H1 also shares sentences with these, for which no sentence is quoted: autism spectrum disorder (4 papers); Charcot-Marie-Tooth disease (3); axonal Charcot-Marie-Tooth disease type 2O (2); genetic disease (2); hepatocellular carcinoma (2); Hyperinsulinemia (2); juvenile amyotrophic lateral sclerosis (2); muscular dystrophies (2); acute myeloid leukemia (1); Ataxia (1); atherosclerosis (1); autosomal dominant intellectual disability (1); autosomal dominant mental retardation- (1); axonal neuropathy (1); Baraitser-Winter syndrome (1); beta thalassaemia (1); brain malformations (1); Charcot-Marie-Tooth disease type 2 (1); complex hereditary spastic paraplegia (1); convulsion (1); cortical dysplasia (1); dementia (1); depression (1); developmental and epileptic encephalopathy (1); diabetes (1); distal spinal muscular atrophy (1); Down syndrome (1); Dyskinesia (1); Dystonia (1); early infantile epileptic encephalopathy (1).
A further 26 diseases each share a sentence with DYNC1H1 in 1 paper.